USHBP1 (USH1 protein network component harmonin binding protein 1)
Synonyms: AIEBP; MCC2; FLJ38709
Tractability: No criterion of Open Targets' tractability assessment is met for any kind of drug.
Gene: Protein-coding gene on chromosome 19 (17,249,171 to 17,282,786, reverse strand). Ensembl gene ENSG00000130307.
Subcellular location (Human Protein Atlas): Nucleoli
Gene Ontology:
Molecular function: PDZ domain binding; protein binding
Genetic constraint (gnomAD): Loss-of-function variants: 67 observed, 77.53 expected, observed/expected ratio (o/e) 0.86, 90% interval 0.71 to 1.06. The upper end of that interval is the gene's LOEUF score, 1.06, which puts it in group 4 of 6, group 1 being the genes least tolerant of losing a copy. Missense variants: 931 observed, 933.09 expected, observed/expected ratio (o/e) 1, 90% interval 0.94 to 1.05. Synonymous variants: 322 observed, 369.17 expected, observed/expected ratio (o/e) 0.87, 90% interval 0.8 to 0.96.
Homologues: Orthologues: macaque USHBP1 (94% identical), dog USHBP1 (76% identical), pig USHBP1 (75% identical), rat Ushbp1 (60% identical), mouse Ushbp1 (58% identical), zebrafish ushbp1 (20% identical), Drosophila melanogaster CG34404 (18% identical). Paralogues in human: MCC (27% identical).
Diseases named in the same sentence as USHBP1 in open-access papers:
USHBP1 is named in the same sentence as 21 diseases in open-access papers, as found by Europe PMC text mining. Sharing a sentence is not in itself a finding about the gene and the disease. The quoted sentences say what the papers report.
schizophrenia (2 papers, 2013 to 2020). A major psychotic disorder characterized by abnormalities in the perception or expression of reality. "The identified polymorphisms and the corresponding genes NR2F6, USHBP1 and BABAM1 have not previously been associated with schizophrenia or other neuropsychiatric disorders." (PMID 23805179, 2013). "Elucidating the specific mechanisms of NR2F6, USHBP1 and BABAM1 in the regulation of neurodevelopment and synaptic (re)organization could improve our conceptual framework of processes related to hippocampal volume reduction and facilitate a better understanding of schizophrenia." (PMID 23805179, 2013).
tumor (2 papers, 2020 to 2021). "We also found that the expression of these 5 genes, namely, ANGPT2, EMCN, GLDN, USHBP1 and ZNF532, was significantly upregulated in HCC tumor tissues compared to the adjacent normal liver tissues in the TCGA and ICGC datasets." (PMID 32644941, 2020). "Another fact that suggests the anti-tumoral potential of the proposed treatment was the upregulation of USHBP1 (FC = 1.50), also known as MCC2; this gene is not expressed in different kind of tumors and, together with its homologue MCC1, is considered a tumor suppressor." (PMID 34683922, 2021).
USHBP1 also shares sentences with these, for which no sentence is quoted: cancer (2 papers); colorectal cancer (2); deafness (2); Usher syndrome (2); bladder cancer (1); Blindness (1); breast carcinoma (1); cervical cancer (1); esophageal cancer (1); gastric cancer (1); genetic disorder (1); head and neck cancer (1); kidney cancer (1); leukemia (1); liver cancer (1); lung carcinoma (1); lymphoma (1); Usher syndrome type 1C (1); viral infection (1).